SUCLG2 (succinate-CoA ligase GDP-forming subunit beta)
Diseases named in the same sentence as SUCLG2 in open-access papers (continued):
Sharing a sentence is not in itself a finding about the gene and the disease.
tumor (19 papers, 2021 to 2026). "The association between high SUCLG2 expression and aggressive PCa features, such as advanced tumor stage and poor prognosis, dovetails with recent discoveries in metabolic oncology." (PMID 40747103, 2025). "Both SMOX and SUCLG2 exhibited significant correlations with cancer prognosis, tumor microenvironment, immune infiltration, stemness scores, tumor mutational burden, and microsatellite instability." (PMID 40699864, 2025). "The association of SUCLG2 with these cellular subsets suggests a link between metabolic processes and cellular differentiation states within the tumor microenvironment." (PMID 40747103, 2025). "High SUCLG2 expression is associated with enhanced immunotherapy response 25, potentially by modulating succinate metabolism, a process implicated in immune cell activation and tumor microenvironment reprogramming." (PMID 40861812, 2025). "Moreover, the presence of SUCLG2 in basal/intermediate cells hints at the metabolic flexibility of these cells, which may underlie their role in tumor initiation and resistance to therapy." (PMID 40747103, 2025). "That is, samples with elevated SUCLG2 levels were predominantly associated with cell cycle checkpoints and protein secretion pathways that were indicative of the potential mechanisms by which SUCLG2 may contribute to tumor aggressiveness." (PMID 40747103, 2025). "In the analysis of the tumor microenvironment (TME), SMOX and SUCLG2 showed close associations with ESTIMATE, immune, and stromal scores, and with tumor purity in COAD, READ, and several other cancers (p < 0.05)." (PMID 40699864, 2025). "IHC revealed that the expression levels of Ki-67 and SUCLG2 were significantly higher in wild-type tumour tissues than in SUCLG2-silenced tissues." (PMID 41249152, 2025). "The results unequivocally confirmed higher expression levels of SUCLG2 in tumor tissues, reinforcing its relevance in PCa pathology." (PMID 40747103, 2025). "Compared with that in the wild type, silencing SUCLG2 significantly inhibited tumour growth and prolonged the survival time of the mice." (PMID 41249152, 2025). "We analysed the differentially expressed proteins identified through proteomic analysis of the tumour periphery and core tissues to explore the anti-tumour mechanism of SUCLG2 in promoting the malignant progression of GBM." (PMID 41249152, 2025). "Future studies employing animal models and patient-derived tumor xenografts are essential to validate the therapeutic potential of targeting SUCLG2 in PCa." (PMID 40747103, 2025). "In particular, SUCLG2 was significantly enriched in luminal and basal/intermediate cell subsets, highlighting its potential role in tumor progression and therapy resistance." (PMID 40747103, 2025). "Specifically, the mechanistic role of SUCLG2 in PCa, especially in terms of its impact on tumor growth, metastasis, and response to therapy, remains to be fully elucidated." (PMID 40747103, 2025). "We used GBM magnetic resonance spectroscopy imaging to compare the metabolic characteristics of the tumour core and peripheral regions for further probing of the regulatory role of SUCLG2 in metabolism." (PMID 41249152, 2025). "Immunofluorescence analysis revealed a marked reduction in lactate levels within tumour tissues following SUCLG2 knockdown, further elucidating the impact of SUCLG2 knockdown on mitochondrial metabolism." (PMID 41249152, 2025). "Immunohistochemical data from The Human Protein Atlas further corroborated the elevated expression of SUCLG2 in PCa tissues, particularly within glandular epithelial cells, thus providing a histological perspective on its role in tumor biology." (PMID 40747103, 2025). "Conversely, samples with lower SUCLG2 expression were enriched in pathways related to epithelial–mesenchymal transition and inflammatory responses, highlighting the multifaceted roles of SUCLG2 in tumor biology." (PMID 40747103, 2025).
tumor (continued). "To validate the differential expression of SUCLG2 in PCa, we conducted qPCR analysis to compare the mRNA expression of SUCLG2 in 10 pairs of tumor tissues and adjacent normal tissues." (PMID 40747103, 2025). "Accordingly, immunofluorescence analysis of the PCa epithelial cell line 22Rv1 revealed the cytoplasmic localization of SUCLG2 and provided insights into its cellular function and potential mechanism of action in tumor progression." (PMID 40747103, 2025). "In vitro assays further demonstrated that L-Lac treatment markedly enhanced malignant tumour progression, whereas silencing of SUCLG2 led to a notable decrease in lactate levels, inhibiting tumour growth." (PMID 41249152, 2025). "Following intracranial implantation of LN229 cells, it was demonstrated that knocking down SUCLG2 significantly reduced lactate concentrations within tumour tissue." (PMID 41249152, 2025). "The core region of GBM is characterised by elevated SUCLG2 expression and an L-lac-rich microenvironment, which promotes malignant-tumour progression." (PMID 41249152, 2025). "Compared with the tumour periphery, SUCLG2 protein expression was significantly elevated in the core GBM region (fold change >2.5; false discovery rate ≤0.001)." (PMID 41249152, 2025). "Inversely, tumours that possessed neuroendocrine PCa features (NEPC) were negatively associated with these genes, notably HIBCH and SUCLG2." (PMID 39025852, 2024). "The results demonstrated that tumor tissues expressed significantly higher levels of SUCLG2 compared to the adjacent normal tissues; this result was further validated by quantification of the staining." (PMID 37904651, 2023). "To confirm these results, we performed immunohistochemistry (IHC) analysis of the tumor samples of A549‐WT and A549‐SUCLG2‐KO using anti‐Ki67, anti‐TTF1, and anti‐SUCLG2 antibodies." (PMID 37904651, 2023). "To provide a theoretical basis for developing anti‐tumor drugs by targeting SUCLG2, we depleted endogenous SUCLG2 and stably reintroduced wild‐type SUCLG2 (SUCLG2WT) or the SUCLG2K93R mutant into A549 cells." (PMID 37904651, 2023). "In LUAD, succinylation on Lys93 increases SUCLG2 stability, leading to metabolic reprogramming and tumor progression." (PMID 37904651, 2023). "In our study, clinicopathological parameter sage, tumor stage, lymphatic, hematogenous metastases and SUCLG2, SUCLG1, ACLY, SUCLG2P2, ATIC and ACO2 genes were found to be associated with survival in univariable or multivariate analysis." (PMID 34589110, 2021). "Pearson analysis showed that SUCLG2P2, SUCLG2 and ATIC were correlated in normal COAD tissues, while only SUCLG2P2 and SUCLG2 were correlated in tumor tissues." (PMID 34589110, 2021). "Additionally, exploring SUCLG2’s interactions with the tumor microenvironment and its influence on cellular metabolism within the context of a living organism will offer a more comprehensive understanding of its role in cancer progression." (PMID 40747103, 2025). "Furthermore, SUCLG2 expression was significantly and positively correlated with the tumour pathological grade." (PMID 41249152, 2025). "SUCLG2 has been implicated in several key metabolic processes critical to cancer metabolism, including the tricarboxylic acid (TCA) cycle, and represents a link between altered metabolic pathways and tumor biology." (PMID 40747103, 2025). "In early-stage tumors, SUCLG2 may promote biosynthetic and proliferative programs, while in inflamed or therapy-resistant settings, reduced SUCLG2 may shift the tumor state toward EMT and immune evasion." (PMID 40747103, 2025). "The presence of SUCLG2 in both may indicate its involvement in both proliferative and adaptive metabolic programs, contributing to tumor heterogeneity and progression." (PMID 40747103, 2025). "A549 SUCLG2‐KO showed a decrease in tumor weight and volume compared with A549‐WT cells." (PMID 37904651, 2023).
tumor (continued). "Conversely, the expression of protective types (ACOX1, CPT2, ELOVL6, SUCLG2) was reduced in the H-R cohort than in the L-R cohort, implying that the eight-gene model accurately predicted prognosis and their possible effect on tumor incidence and growth." (PMID 38186579, 2023). "This study discovers a new function for SUCLG2 in tumor progression." (PMID 37904651, 2023). "Hence, we aimed to retrospectively collect pathologically identified PPGL tumor tissues from our center and investigate the expression of apelin and SUCLG2 along with previously studied ERBB-2, CNTN4, CHGB, and SDHB in metastatic and non-metastatic PPGLs." (PMID 35574028, 2022). "Besides, it has been reported that the interaction between tumor and microenvironment is inhibited by metformin through SUCLG2." (PMID 34589110, 2021). "SUCLG2 mRNA expression levels in all samples were lower in tumor tissues (P < 0.001)." (PMID 34589110, 2021). "This subtle relationship suggests that lexibulin, in particular, might be more suitable for patients with lower SUCLG2 levels and present a therapeutic avenue that could potentially protect patients from unnecessary toxicity while targeting the tumor more effectively." (PMID 40747103, 2025). "Thus, we speculated that SUCLG2 might affect tumor proliferation by regulating mitochondrial metabolism." (PMID 37904651, 2023). "Succinylation at lysine 93 (K93) enhances the stability of the SUCLG2 protein, thereby facilitating LUAD cell proliferation and tumor progression." (PMID 40865948, 2025). "Second, attempts to rescue cell proliferation and migration by supplementing with glutamine or 2-KG fail in SUCLG2 KO cells, suggesting that SUCLG2 functions downstream of ODC and is essential for the tumor-suppressive effects of ODC." (PMID 39795950, 2024). "The expression levels of CD36, PTGR1, SUCLG2 and CPT2 were significantly decreased in tumor tissues." (PMID 36568396, 2022). "We considered the combination of SUCLG2 and SUCLG2P2 with common miRNA to achieve consistent expression and exert a tumor suppressor effect to affect the prognosis of patients." (PMID 34589110, 2021). "Analyzing the downloaded TCGA data showed that the expression of ATIC was up-regulated in the tumor, and that of SUCLG2P2 was consistent with that of SUCLG2, the mRNA expression of SUCLG2P2 and SUCLG2 were down-regulated in the tumor." (PMID 34589110, 2021). "We also confirmed the expression levels of SUCLG2P2, SUCLG2 and ATIC mRNA in tumor and non-tumor tissues from 10 patients with CRC." (PMID 34589110, 2021). "Differential expression analysis of these 27 intersecting genes in the GSE87211 dataset from GEO revealed significant expression differences between tumor and normal groups for 26 genes, with ASCL2, IFITM3, IFITM1, SMPDL3A, and SUCLG2 being the five most significantly differentially expressed." (PMID 41595533, 2026). "Taken together, our study elucidates the role of SUCLG2 in mitochondrial dysfunction and clarifies the mechanism of the succinylation‐mediated protein homeostasis of SUCLG2 in LUAD, thereby providing a theoretical basis for developing anti‐tumor drugs by targeting SUCLG2." (PMID 37904651, 2023). "The expression of CD36, PTGR1, SUCLG2, CPT2 and ELOVL6 were downregulated in tumor tissues." (PMID 36568396, 2022). "Genes and proteins regulating the TCA cycle (PDHA1, SUCLG2, SUCLG1, and IDH2) as well as mitochondrial function (VDAC1, MRPS31, LARS2, OPA1, and MTIF2) showed higher transcripts and protein levels in Wnt‐high compared with Wnt‐low tumor entities." (PMID 35904277, 2022). "Consequently, HIGD1A, SUCLG2, and SLC25A24 were all down-regulated in CRC and exhibited a stably declined expression throughout the tumor progression." (PMID 34174878, 2021).
tumor (continued). "Thus, our study elucidates the role of SUCLG2 in mitochondrial dysfunction and clarifies the mechanism of the succinylation‐mediated protein homeostasis of SUCLG2 in LUAD, thereby providing a theoretical basis for developing anti‐tumor drugs by targeting SUCLG2." (PMID 37904651, 2023). "As SUCLG2 depletion‐mediated mitochondrial dysfunction contributed to LUAD inhibition, we hypothesized that the downregulation of SUCLG2 might be a potentially feasible strategy to block tumor growth." (PMID 37904651, 2023).
cancer (11 papers, 2021 to 2025). A tumor composed of atypical neoplastic, often pleomorphic cells that invade other tissues. "Herein we analyzed SMOX and SUCLG2 expression trends in pan-cancer and explored the association of SMOX and SUCLG2 with cancer prognosis, immunity, cancer cell characteristics, and drug sensitivity." (PMID 40699864, 2025). "In the future, we aim to further investigate the molecular mechanisms of SMOX and SUCLG2 in cancer and potentially offer new diagnostic and treatment approaches for cancers." (PMID 40699864, 2025). "In this study, SMOX and SUCLG2 were differentially expressed in pan-cancer tissues and associated with cancer prognosis." (PMID 40699864, 2025). "Our data provide insights into the role of SMOX and SUCLG2 in pan-cancer, highlighting their association with prognosis, cancer immunity, and other cancer characteristics and also revealing their significance in cancer progression." (PMID 40699864, 2025). "Expression patterns and underlying mechanisms of metabolism-related genes SMOX and SUCLG2 in pan-cancer remain unclear." (PMID 40699864, 2025). "SMOX and SUCLG2 were found to be strongly associated with pan-cancer immunophenotypes (p < 0.001)." (PMID 40699864, 2025). "In blood (GSE10715 and GSE174032) and tissue (GSE39582 and GSE44076) samples, relative to the normal groups, the expression of SMOX increased while that of SUCLG2 decreased in the cancer groups." (PMID 40699864, 2025). "While these approaches have provided valuable insights into the potential mechanisms by which SUCLG2 contributes to PCa, the complexity of cancer biology necessitates further validation through in vivo and ex vivo experiments." (PMID 40747103, 2025). "Herein, our pan-cancer analysis indicated that SMOX was highly expressed and SUCLG2 was less expressed in most cancers." (PMID 40699864, 2025). "Our results indicate an association between SMOX, SUCLG2, MSI, and TMB in various cancers, suggesting the potential of SMOX and SUCLG2 as immunotherapy predictors." (PMID 40699864, 2025). "Similar outcomes were observed in TCGA dataset, where SMOX expression increased while SUCLG2 expression decreased in cancer tissues." (PMID 40699864, 2025). "To summarize, our pan-cancer analysis of SMOX and SUCLG2 demonstrated their close association with clinical characteristics, prognosis, cancer immunity, cancer cell characteristics, and drug sensitivity in various cancers." (PMID 40699864, 2025). "Our findings revealed a close relationship between SMOX, SUCLG2, clinical characteristics, cancer immunity in CRC." (PMID 40699864, 2025). "Survival analysis in pan-cancer revealed that SMOX and SUCLG2 acted as independent prognostic factors in multiple cancers, and high SMOX expression or low SUCLG2 expression was associated with worse prognosis." (PMID 40699864, 2025). "The Cancer Genome Atlas database and Gene Expression Profile Interaction Analysis 2 results showed that SUCLG2 expression levels were significantly higher in GBM samples than in normal tissues." (PMID 41249152, 2025). "Pathway enrichment analysis involving gene set enrichment analysis revealed that SMOX and SUCLG2 regulate drug metabolism, antigen presentation, and other related pathways, indicating their close relationship with cancer immunity and drug sensitivity." (PMID 40699864, 2025). "This indicates that SIRT5‐mediated succinylation regulation is mediated not only by its direct binding to the desuccinylation substrate but also by the regulation of SUCLG2 expression to influence overall succinylation in cancer cells." (PMID 37904651, 2023). "Statistical analysis of the staining quantification results of the cancer tissues divided the samples into two groups depending upon the SUCLG2 level." (PMID 37904651, 2023). "Our findings highlight that SMOX and SUCLG2 are significantly correlated with cancer immunity." (PMID 40699864, 2025). "The expression of SMOX was upregulated and that of SUCLG2 was downregulated in most cancers." (PMID 40699864, 2025).
cancer (continued). "SMOX and SUCLG2 participate in cancer development and initiation." (PMID 40699864, 2025). "SMOX and SUCLG2 play a vital role in cancerogenesis, particularly in cancer metabolism; however, their roles in pan-cancer remain unclear." (PMID 40699864, 2025). "This further reflects the different roles of SUCLG2 in different cancers." (PMID 40699864, 2025). "Thus, the functions of SUCLA2 and SUCLG2 differ depending on the cancer type." (PMID 37904651, 2023). "On the other hand, SUCLG2 activity was the highest in THCA and lowest in SARC, differing from normal tissues in cancers such as CHOL, COAD, and READ, with most of them showing a downward trend." (PMID 40699864, 2025). "We conducted a comprehensive pan-cancer analysis of SMOX and SUCLG2, to explore their potential roles and mechanisms of action." (PMID 40699864, 2025). "On the other hand, decreased expression of SUCLG2 can enhance the inhibition of TGF-β signal transduction in cancer stroma through metformin, affecting the promoting effect of TME on cancer cell growth." (PMID 40699864, 2025). "In this manner, a negative correlation was observed between SMOX and SUCLG2 expression in pan-cancer, consistent with gene expression patterns." (PMID 40699864, 2025). "Notably, the expression of ECI2, MCCC2, SUCLG2, and CPT2 was higher and that of OXCT1 was lower in cancer tissues than in para‐cancer tissues." (PMID 39491527, 2024). "Among these genes, ANXA2R (Annexin A2 Receptor), RBM3 (RNA-binding Protein 3), and SUCLG2 (Succinyl-CoA ligase [GDP-forming] subunit β), which may act as cancer drivers, were downregulated." (PMID 39766901, 2024). "The findings reveal a new role for SUCLG2 in mitochondrial dysfunction and clarify the mechanism of the succinylation‐mediated protein homeostasis of SUCLG2 in LUAD, thus providing a theoretical basis for developing anti‐cancer drugs targeting SUCLG2." (PMID 37904651, 2023). "SMOX and SUCLG2 expression levels in 56 pairs of CRC and adjacent normal colorectal tissues were measured by qPCR, which indicated that relative to normal tissues, SMOX was increasingly expressed and SUCLG2 was decreasingly expressed in cancer tissues (p < 0.05)." (PMID 40699864, 2025). "However, the role of the top three genes (MMAA, SUCLG2 and CBR4) negatively correlated with POLD1 expression in cancers is not elucidated." (PMID 35189839, 2022).
adenocarcinoma (1 paper, 2022). A common cancer characterized by the presence of malignant glandular cells. "However, SUCLG2 expression has been found to be not significantly different between t-NEPC and high-grade adenocarcinoma patients, indicating that LIFR activation and STAT3 signaling are not exclusive regulators of SUCLG2 in t-NEPC." (PMID 35109899, 2022).
infection (1 paper, 2023). The state of being infected such as from the introduction of a foreign agent such as serum, vaccine, antigenic substance or organism. "Moreover, a decreased expression of enzyme subunits (MDH2 and SUCLA2) and an elevated expression of ACO1 and SUCLG2 in the cycle were observed post infection." (PMID 37256871, 2023).
metabolic disorder (1 paper, 2025). "Our study observed an overall metabolic disorder in the TCA cycle related to the downregulation of circPSD3 and SUCLG2, characterized by succinate deficiency." (PMID 40925894, 2025).